CDKAL1 (CDKAL1 threonylcarbamoyladenosine tRNA methylthiotransferase)
Diseases named in the same sentence as CDKAL1 in open-access papers (continued):
Sharing a sentence is not in itself a finding about the gene and the disease.
type 2 diabetes (continued). "Cyclin-dependent kinase 5 (CDK5) regulatory subunit-associated protein 1-like (CDKAL1) is required for normal mitochondrial morphology and function in pancreatic islets and other tissues such as adipose tissue, which can contribute to the pathogenesis of type 2 diabetes." (PMID 33810109, 2021). "However, our previous study found an interaction between the risk-conferring G-allele of CDKAL1 variants in coffee consumption and type 2 diabetes and prediabetes, but, when we further expanded our analysis to a larger population, we did not observe a significant interaction anymore." (PMID 32722593, 2020). "CDK5 regulatory subunit associated protein 1-like 1 (CDKAL1) was recently identified as a susceptibility gene for type 2 diabetes (T2D) in genome-wide association studies." (PMID 27139004, 2016). "Their data suggest CDKAL1-v1-mediated CDKAL1 gene may underlie type 2 diabetes pathogenesis." (PMID 25477902, 2014). "In addition, the selection of the derived rs7754840 allele in East Asians may explain part of the observed differences in association strength between CDKAL1 and type 2 diabetes among human populations." (PMID 25222615, 2014). "We identified fourteen type 2 diabetes-associated genes discovered by the first waves of GWAS for which there was little prior evidence of their potential role in diabetes (Adam30, Adamts9, Camk1d, Cdc123, Cdkal1, Cdkn2a, Cdkn2b, Ext2, Hhex, Ide, Jazf1, Lgr5, Thada and Tspan8)." (PMID 23442068, 2013). "The complex interplay between insulin secretion, insulin sensitivity, and dietary habits in relation to glucose metabolism led us to hypothesize that type 2 diabetes risk loci including CDKAL1 could exert some protective effects on fat accumulation, which was represented by BMI in the present study." (PMID 23173044, 2012). "However, in 2007, several reproducible genome-wide association studies (GWASs) confirmed these well-established susceptibility genes and identified a number of new loci (SLC30A8, HHEX, CDKN2A/B, IGF2BP2, GCKR, FTO, and CDKAL1) at which common variants influence risk of type 2 diabetes in Europeans." (PMID 20161779, 2010). "In the future, all variants of TCF7L2, KCNQ1, and CDKAL1 could be genotyped to classify clusters of newly diagnosed type 2 diabetes (T2D) in large, multi-centre studies with long-term follow-up." (PMID 41422334, 2025). "Polymorphisms of TCF7L2, IGF2BP2, CDKAL1, KCNQ1, and PPARG genes showed a strong contribution to type 2 diabetes." (PMID 36902173, 2023). "It showed hypertrophy of islets, reduced insulin secretion, and impaired glycemic control, which are typical phenotypes related to type 2 diabetes in CDKAL1 knockout mice." (PMID 36923941, 2023). "CDKAL1: Variants in the CDK5 Regulatory Subunit Associated Protein 1-Like 1 (CDKAL1) gene, involved in cell cycle regulation, compromise beta-cell function and increase the risk of type 2 diabetes." (PMID 37965396, 2023). "In individuals with type 2 diabetes treated with DPP-4i, the HbA1c reduction after 6 months varied according to two CDKAL1 SNPs (rs7754840, G>C, intron variant; rs756992, A>G)." (PMID 33594477, 2021). "The strongest associations between type 2 diabetes risk alleles and lower birthweight are at loci that primarily affect pancreatic beta cell function (e.g. ADCY5 and CDKAL1)." (PMID 33569631, 2021). "Genetic polymorphisms in CDKAL1, CDKN2A/2B, KCNJ11, KCNQ1, and PEPD that we selected as potential effect modifiers were found to be associated with type 2 diabetes in the East Asian population." (PMID 32722593, 2020). "This is contrary to what has been seen at other Type 2 diabetes loci such as ADCY5 and CDKAL1, where risk alleles in the fetus were associated with lower birth weight." (PMID 29309628, 2018). "CDKAL1 rs10946398 is a type 2 diabetes (T2D)-associated variant." (PMID 30185902, 2018).
type 2 diabetes (continued). "Taken together, these findings in adipose tissue suggest that the type 2 diabetes GWAS candidate gene Cdkal1 has a functional role in regulating mitochondrial function in vivo." (PMID 29031721, 2017). "We measured mRNA levels of type 2 diabetes GWAS genes, including Cdkal1, in adipose tissue from lean and obese mice." (PMID 29031721, 2017). "Our results identify CDKAL1 as novel negative regulator of adipocyte differentiation and provide insights into the link between CDKAL1 and metabolic diseases such as type 2 diabetes and obesity." (PMID 28779110, 2017). "We have previously confirmed the associations of genetic variants in HHEX, CDKAL1, VEGFA and FTO with type 2 diabetes in Han Chinese." (PMID 25587982, 2015). "Evidence from previous GWA studies suggest cell cycle dysregulation as a common mechanism in type 2 diabetes; for example, type 2 diabetes association signals are found close to the cell cycle regulator genes, CDKN2A/CDKN2B and CDKAL1." (PMID 25211022, 2014). "In light of the recent report that the type 2 diabetes candidate gene CDKAL1 is a tRNA methylthiotransferase, the findings in this family suggest broader relevance of tRNA methyltransferases in the pathogenesis of type 2 diabetes." (PMID 24204302, 2013). "As a whole, there appears to be a tendency of inverse correlation between the OR for type 2 diabetes at CDKAL1 and BMI." (PMID 23173044, 2012). "The similarity of these loci to those associated with type 2 diabetes, namely, TCF7L2 and CDKAL1, led the authors to propose that GDM and type 2 diabetes were different manifestations of the same genetic entity." (PMID 22577574, 2012). "We have identified significant association between variants in CDKN2A/B, CDKAL1 and TCF7L2, and type 2 diabetes in a Han Chinese cohort, indicating these genes as strong candidates conferring susceptibility to type 2 diabetes across different ethnicities." (PMID 20161779, 2010). "In summary, we have identified significant associations between variants in CDKN2A/B, CDKAL1 and TCF7L2 and type 2 diabetes in a Han Chinese population." (PMID 20161779, 2010). "In conclusion, we confirmed the association between PPARG, KCNJ11, CDKAL1, CDKN2A-CDKN2B, IDE-KIF11-HHEX, IGF2BP2, SLC30A8 variants and type 2 diabetes." (PMID 19862325, 2009). "We confirmed the effects of SNPs from PPARG, KCNJ11, CDKAL1, CDKN2A-CDKN2B, IDE-KIF11-HHEX, IGF2BP2 and SLC30A8 on risk for type 2 diabetes, with odds ratios ranging from 1.114 to 1.406 (P value range from 0.0335 to 1.37E-12)." (PMID 19862325, 2009). "The current study confirmed the association between PPARG, KCNJ11, CDKAL1, CDKN2A-CDKN2B, IDE-KIF11-HHEX, IGF2BP2 and SLC30A8 and type 2 diabetes." (PMID 19862325, 2009). "We recently reported that type 2 diabetes risk alleles in TCF7L2, CDKAL1, and SLC30A8 impair proinsulin-to-insulin conversion." (PMID 19088850, 2008). "Moreover, investigations into common genetic variants linked to type 2 diabetes, such as TCF7L2, SLC30A8, and CDKAL1, underscore the interconnectedness of GDM and metabolic disorders." (PMID 38694942, 2024). "CDKAL1 is involved in the pathogenesis of diabetes type 2 through impaired β-cell function." (PMID 37628646, 2023). "Genetic variants in or near the CDKAL1, KLF9, GP2, ALDH2, and ITIH4 genes are associated with obesity and genetic variants in or near the GDAP1, PTF1A, SIX3, ALDH2, and PAX4 genes are specifically associated with type 2 diabetes in East Asians." (PMID 37749090, 2023). "A previous study has found that Cdkal1 knockout mice develop and grow normally except for an elevated susceptibility to type II diabetes, suggesting that CDKAL1 is not essential for maintaining somatic cells in normal tissues." (PMID 36786012, 2023). "Several GWASs have revealed the role of CDKAL1 in type 2 diabetes." (PMID 35565529, 2022).
type 2 diabetes (continued). "After correction for multiple testing, type 2 diabetes–associated SNPs in or near HHEX, CDKAL1, IGF2B2, fasting glucose–associated SNPs in or near CDKAL1 and IGF2BP2, and a 2-hour glucose post-OGTT–associated SNP at the GIPR locus were all associated with beta-cell glucose sensitivity." (PMID 32944759, 2021). "We did not detect statistically significant interactions between coffee consumption and five SNPs related to type 2 diabetes (CDKAL1 rs7756992, CDKN2A/B rs10811661, KCNJ11 rs5215, KCNQ1 rs163184, and PEPD rs3786897) in the association between coffee and the risk of type 2 diabetes." (PMID 32722593, 2020). "The mechanism on how CDKAL1 interacts with dietary fat and protein intake for type 2 diabetes remains unclear." (PMID 32764395, 2020). "The Helsinki Birth Cohort Study investigated the interaction between birth weight and CDKAL1-rs7754840 on the risk of developing type 2 diabetes, and the results were negative." (PMID 33353041, 2020). "Famine exposure weakened the effect of CDKAL1-rs10946398 to type 2 diabetes." (PMID 33353041, 2020). "For type 2 diabetes, we found evidence of a recessive effect at the CDKAL1 locus." (PMID 26961502, 2016). "The small effect of rs9366357 on diabetes risk leads us to conclude that dysregulated expression of CDKAL1-v1 is unlikely to be the only genotype-dependent defect driving the association between genetic variation at the CDKAL1 locus and type 2 diabetes risk." (PMID 25634229, 2015). "A majority of genes associated with type 2 diabetes from this meta-analysis (ADCY5, CDKAL1, CDKN2A/B, HHEX, IGF2BP2, SLC30A8, TCF7L2 and KCNQ1) are involved in pancreatic beta cell function, while two are implicated in insulin sensitivity (PPARG) and adiposity (FTO)." (PMID 25145545, 2014). "Based on an analysis of the evolutionary history of candidate genes, we showed that common 5′ variants in CDKAL1, CYB5R4, GAD2, and PPARG as well as an intronic type 2 diabetes-associated CDKAL1 variant exhibit non-neutral evolutionary patterns." (PMID 25222615, 2014). "Moreover, it was reported that rs7756992, a common variant in CDKAL1 loci (MAF = 0.479), contributed to type 2 diabetes risk in Han Chinese in a study with a similar sample size." (PMID 23990951, 2013). "In Cdkal1-deficient mice, we tested the hypothesis that changes in the activity of Cdkal1 result in islet dysfunction and/or insulin resistance, thereby contributing to the pathogenesis of type 2 diabetes." (PMID 23173044, 2012). "Most of the genes associated with type 2 diabetes (TCF7L2, SLC30A8, HHEX, CDKAL1, CDKN2A/B and IGF2BP2) might be implicated in beta cell function." (PMID 20161779, 2010). "GWASs have recently described novel type 2 diabetes susceptibility loci, including several previously unknown genomic regions, such as CDKN2A/B and CDKAL1." (PMID 20161779, 2010). "We replicated previous findings of associations for three SNPs in this Chinese population (rs10811661 in CDKN2A/B, rs10946398 in CDKAL1, and rs7903146 in TCF7L2) suggesting that some of the variants associated with type 2 diabetes in Europeans are also associated with the disease in Asians." (PMID 20161779, 2010). "In addition, SNPs from PPARG, KCNJ11, CDKAL1, IDE-KIF11-HHEX, IGF2BP2 and SLC30A8 were also moderately associated with type 2 diabetes, with ORs ranging from 1.114 to 1.282 (P<0.05)." (PMID 19862325, 2009). "However, after correction of multiple comparisons, only the association between SNPs from CDKAL1, CDKN2A-CDKN2B, IDE-KIF11-HHEX, IGF2BP2 and SLC30A8 and type 2 diabetes remained to be significant." (PMID 19862325, 2009). "Together, our data support a model wherein perturbing Cdkal1 expression may produce effects on mitochondrial function in islets and other tissues like skeletal muscle, which may contribute to the pathogenesis of type 2 diabetes." (PMID 29031721, 2017). "Manipulation of CDKAL1 activity may be useful for treatment of obesity and type 2 diabetes." (PMID 28779110, 2017).
type 2 diabetes (continued). "The association of type 2 diabetes mellitus (T2DM) with the KCNJ11, CDKAL1, SLC30A8, CDKN2B, and FTO genes in the Russian population has not been well studied." (PMID 28717589, 2017). "However, we found replicable examples of non-additive effects at FTO on BMI and obesity, and at CDKAL1 on type 2 diabetes risk." (PMID 26961502, 2016). "Analogously in the human, as dietary habits substantially influence BMI in the population at large, genetic effects on type 2 diabetes, attributable to CDKAL1, may differ between populations (or ethnic groups) with distinct dietary habits and the resultant cross-population diversity in BMI." (PMID 23173044, 2012). "Recently, several genome-wide and candidate gene association studies have identified many novel genetic loci for type 2 diabetes (T2D); among these genes, CDKAL1, IGF2BP2, SLC30A8, CDKN2A/B, HHEX, FTO, TCF2, KCNQ1, and WFS1 are the most important." (PMID 20509872, 2010). "Notably, a CDKAL1 variant (rs7766070) confers the highest level of risk while rs7119 (HMG20A) and rs708272 (CETP) have high risk allele frequencies in this population at 0.77 and 0.66, respectively, making them potentially good markers for type 2 diabetes mellitus screening." (PMID 39561140, 2024). "Type 2 diabetes, AD, and Parkinson’s disease are predicted to share similar dysregulated pathways involving TCF7L2 and CDKAL1." (PMID 38790243, 2024). "Separately, although the regulatory elements implicating SOX4 –a gene involved in insulin secretion–overlapped with a different gene (CDKAL1), this distal locus has indeed previously been studied and found to incriminate SOX4 in the context of type-2 diabetes." (PMID 35316269, 2022). "We found that loci near TMEM18 (rs6548238), CDKAL1 (rs7754840), and FAIM2 (rs7138803) may be associated with obesity-related indicators, and loci near TMEM18 (rs6548238) and FAIM2 (rs7138803) may increase susceptibility of concurrent type 2 diabetes associated with obesity." (PMID 32228543, 2020). "In stage 1, 88 SNPs were genotyped in 1,251 patients with type 2 diabetes, and we found that ADAMTS9-AS2 rs4607103, WFS1 rs10010131, CDKAL1 rs7756992, VPS26A rs1802295 and IDE-KIF11-HHEX rs1111875 were significantly associated with DR." (PMID 28821857, 2017). "This study examined the association of the polymorphic markers of the genes KCNJ11, SLC30A8, CDKAL1, CDKN2B and FTO with type 2 diabetes mellitus in Russia." (PMID 28717589, 2017). "However, these associations were abolished or substantially reduced in multiple regression models taking into account rs9366357 genotype: a moderately linked SNP explaining a much larger amount of the variation in CDKAL1-v1 levels, but not strongly associated with risk of type 2 diabetes." (PMID 25634229, 2015). "We further evaluated the cumulative effect on type 2 diabetes of these 4 SNPs, in combination with 5 SNPs at HHEX, CDKAL1, VEGFA and FTO reported previously." (PMID 25587982, 2015). "In this study, we confirmed the effects of variations in PPARG, KCNJ11, CDKAL1, CDKN2A-CDKN2B, IDE-KIF11-HHEX, IGF2BP2 and SLC30A8 on type 2 diabetes." (PMID 19862325, 2009). "For obesity and type 2 diabetes, the strongest evidence of a non-additive effect is at the CDKAL1 locus, where a previous study demonstrated a recessive effect." (PMID 26961502, 2016). "We have previously examined common genetic variation in several candidate gene loci (i.e., KCNQ1, KCNJ11, CDKAL1, and FTO genes) and confirmed some but not all of their associations with type 2 diabetes in the SDS." (PMID 21062480, 2010).
diabetes (47 papers, 2010 to 2026). "The enrichment of TCF7L2, KCNQ1, and CDKAL1 variants in specific subtypes highlights the potential for integrating genetic screening into diabetes stratification models." (PMID 41422334, 2025). "WFS1 also interacts with the insulin release-related proteins (HHEX and CDKAL1), which are strongly associated with genetic risk variants for diabetes." (PMID 37185285, 2023). "The results of this study suggest an association between CDKAL1 gene rs10946398 polymorphism and post-transplant diabetes in kidney allograft recipients treated with tacrolimus." (PMID 37628646, 2023). "The influence of CDKAL1 gene polymorphisms on numerous parameters of carbohydrate and lipid metabolism, as well as on diabetes complications, has also been demonstrated." (PMID 37628646, 2023). "The cumulative effect of CDKAL1 rs7756992 polymorphism and positive family history of diabetes significantly increased the risk of GDM by 2.7-fold under the dominant genetic model." (PMID 35090536, 2022). "In women, significant interactions between dietary protein and fat intake and CDKAL1 variants (rs7756992) were associated with increased risk of diabetes (p-value < 0.05)." (PMID 32764395, 2020). "The current findings support the role of dietary protein and fat intake as useful indicators for diabetes risk in Korean men and women who have CDKAL1 risk alleles." (PMID 32764395, 2020). "Significant relationships between CDKAL1 genetic variants (rs7756992) and dietary protein and fat intake in relation to diabetes were observed in the Korean population from the KoGES-HEXA study." (PMID 32764395, 2020). "A significant association was observed between the rs7756992 CDKAL1 gene variant and the risk of diabetes." (PMID 32764395, 2020). "Cyclin-dependent kinase 5 regulatory subunit-associated protein 1-like 1 (CDKAL1) is one of the strongest diabetes loci identified to date; evidence suggests that it plays an important role in insulin secretion." (PMID 32764395, 2020). "The aim of this study was to explore the interactions between dietary protein and fat intake and CDKAL1 genetic variants in the Korean adult population, to better understand their role in diabetes development." (PMID 32764395, 2020). "Previous findings suggest significant associations between CDKAL1, alcohol intake, dietary fat, and energy intake in relation to diabetes." (PMID 32764395, 2020). "Our aim was to examine the interactions between dietary protein and fat intake and CDKAL1 genetic variants in relation to the risk of diabetes in Korean adults." (PMID 32764395, 2020). "In the Ansan/Ansung Korean cohort, diabetes risk increased by 1.549 (95% CI 1.207–1.720) when high alcohol intake was combined with the presence of CDKAL1 risk alleles." (PMID 32764395, 2020). "Significant interactions between CDKAL1 rs7756992 and dietary protein and fat intake for the risk of diabetes were observed in men (p-value < 0.05)." (PMID 32764395, 2020). "Dietary protein and fat intake interacted differently with CDKAL1 variants in relation to the risk of diabetes in Korean adults of both genders." (PMID 32764395, 2020). "CDKAL1 variants have been shown to predict the development of diabetes in individuals with impaired insulin secretion, which suggests potential synergistic effects between different risk factors." (PMID 32764395, 2020). "In conclusion, dietary protein and fat intake interacted with CDKAL1 variants in relation to the risk of diabetes, which does vary depending on gender." (PMID 32764395, 2020). "Diabetes is caused by genetic and environmental factors, and we found a significant interaction between dietary protein and fat intake and CDKAL1 genetic variants in relation to the risk of diabetes." (PMID 32764395, 2020). "Previous studies have identified an association between diabetes risk and SNPs for CDKAL1 in European Americans, African Americans, UK samples, Indians, Korean, and Chinese, making CDKAL1 one of the most highly replicated genes identified." (PMID 30907055, 2019).